5_8S_rRNA (5.8S ribosomal RNA )
Synonyms: RNA5-8SP; LOC110467521
Gene: Ribosomal RNA gene on chromosome 20 (29,297,095 to 29,297,246, reverse strand). Ensembl gene ENSG00000283568.
Gene Ontology:
Molecular function: structural constituent of ribosome
Cellular component: ribosome
Homologues: Orthologues: chimpanzee 5_8S_rRNA (85% identical). Paralogues in human: 5_8S_rRNA (91% identical), 5_8S_rRNA (90% identical), 5_8S_rRNA (88% identical), RNA5-8SN1 (88% identical), RNA5-8SN2 (88% identical), RNA5-8SN3 (88% identical), RNA5-8SN4 (88% identical), RNA5-8SN5 (88% identical), 5_8S_rRNA (87% identical), 5_8S_rRNA (86% identical).